MAVS (mitochondrial antiviral signaling protein)
Diseases named in the same sentence as MAVS in open-access papers (continued):
Sharing a sentence is not in itself a finding about the gene and the disease.
systemic lupus erythematosus (21 papers, 2014 to 2025). An autoimmune multi-organ disease typically associated with vasculopathy and autoantibody production. "Recent studies have reported MAVS to be associated with various conditions including cancers, systemic lupus erythematosus, kidney disease, and cardiovascular disease." (PMID 40040697, 2025). "Another study not only confirmed that MAVS in B cells is required for the formation of autoreactive GCs and autoantibody production in lupus-susceptible mice, but additionally linked its expression to the development of proteinuria and glomerulonephritis." (PMID 32547564, 2020). "Our findings reveal a decisive role of MAVS in autoimmune GC responses: the development of autoreactive GCs and autoantibody production in lupus susceptible R2−/− mice was nearly completely abrogated by the MAVS deficiency." (PMID 31681326, 2019). "The SNPs in the gene coding for MAVS appeared to be associated with systemic lupus erythematosus in the Chinese population, albeit only in patients with renal nephritis and arthritis, respectively." (PMID 24949794, 2014). "Notably, the systemic lupus erythematosus–associated mutation MAVS C79F was associated with defective palmitoylation, resulting in low type I interferon (IFN) production." (PMID 39621307, 2024). "Upregulation of mitochondrial reactive oxygen species has been associated with enhanced aggregation and activation of MAVS as well as increased expression of type I interferon, which is one of the causes of autoimmune diseases such as systemic lupus erythematosus." (PMID 39141356, 2024). "Two of these reports showed an association between MAVS SNPs and systemic lupus erythematosus (SLE) in African-American and Chinese populations." (PMID 26954674, 2016). "MAVS C79F mutation, which resides close to the CARD that is crucial for the aggregation, relieves the lupus symptoms of patients due to the reduced MAVS aggregation." (PMID 39141356, 2024). "Notably, the systemic lupus erythematosus–related (SLE-related) mutation MAVS C79F, a loss-of-function variant of MAVS, was associated with defective palmitoylation." (PMID 39621307, 2024). "Large MAVS polymers were found in systemic lupus erythematosus patients and believed to play a role in production of type I IFNs and pathogenesis of the disease." (PMID 37610299, 2023). "Recent studies have shown that MAVS is involved in the occurrence and development of many diseases such as cancer, systemic lupus erythematosus(SLE), cardiovascular diseases(CVD), acute kidney injury (AKI), and chronic kidney disease(CKD)." (PMID 37901251, 2023). "In support of these findings, we recently showed that MAVS is required, in a B cell–intrinsic fashion, to regulate the development of autoimmune germinal centers and the production of autoantibodies in a lupus-prone mouse model." (PMID 37610299, 2023). "Recent studies have reported that MAVS is involved in various cancers, systemic lupus erythematosus, kidney diseases, and cardiovascular diseases." (PMID 37901251, 2023). "MAVS was recently found to participate in other diseases, such as systemic lupus erythematosus (SLE)." (PMID 35844503, 2022). "Another study investigated the aggregate forming capacity of MAVS in the PBMCs of systemic lupus erythematosus (SLE) patients, the prion-like aggregation of which leads to enhanced type I IFN signaling that consequently fuels autoimmunity." (PMID 33525671, 2021). "We have previously observed that in T cells from patients with lupus, the increased mROS is capable of provoking oligomerisation of mitochondrial antiviral stimulator (MAVS) and production of type I interferon (IFN-I)." (PMID 32343673, 2020). "We thus investigated further the ability of the mitochondria-targeted antioxidant MitoQ in vivo to reverse mROS and NET formation, MAVS oligomerisation, as well as to test its therapeutic potential on lupus disease manifestations in MRL-lpr mice." (PMID 32343673, 2020).
systemic lupus erythematosus (continued). "The MAVS protein levels were significantly higher in patients with lupus than in normal controls and were negatively correlated with lupus activity in our previous study." (PMID 30105262, 2018). "Additional studies with MAVS mutant and bone marrow chimeric mice will be required to elucidate the specific and combinatorial contributions of the endosomal and cytosolic pathways to spontaneous and virus-enhanced lupus." (PMID 30199535, 2018). "In systemic lupus erythematosus (SLE), both T cells and mesenchymatous stem cells secrete high levels of IFN-I that are associated with mitochondrial dysfunctions, including enhanced mtROS production, and that are reduced by MAVS silencing and ROS inhibition." (PMID 29725325, 2018). "Inappropriate or persistent MAVS aggregation has been linked to increased production of IFN-I and autoimmunity in a significant fraction of Systemic Lupus Erythematosus (SLE) patients." (PMID 37563140, 2023). "Hence, we examined whether a similar phenomenon of enlarged mitochondria and spontaneous MAVS oligomerisation might occur in any of the T-cell subsets of lupus-prone MRL-lpr mice." (PMID 32343673, 2020). "Here we show that MAVS, an essential adaptor for RIG-I/MDA5 signaling, is necessary for all symptoms of autoimmune disease that develop spontaneously in the lupus model FcγRIIB−/− mice." (PMID 31681326, 2019). "Consistent with their primary role in spontaneous lupus, pDCs and the endosomal TLR pathway of innate immune activation were found to be necessary for disease acceleration in NZB mice, despite the efficient induction of IFN-I by viral RNA via cytosolic helicases and MAVS." (PMID 30199535, 2018).
COVID-19 (17 papers, 2020 to 2025). A disease caused by infection with severe acute respiratory syndrome coronavirus 2. "The activation of interferon-stimulated genes (ISG) such as, 2’-5’-oligoadenylate synthetase (OAS1) and mitochondrial antiviral-signaling protein (MAVS) are associated with mild COVID-19." (PMID 41468475, 2025). "We determined the association between LTBi positivity with severity of COVID-19 as well as mRNA expression of immune related genes including those required for MTB as well as SARS-CoV-2 control; IFN-γ, IFN-α, IL-6, IL-10, OAS1, MAVS, SOCS1 and SOCS3 molecules." (PMID 41468475, 2025). "A gene variant of NUDCD1 influences COVID-19 severity in Asians through interacting with DHX15 and MAVS, affecting effective response against SARS-CoV-2." (PMID 40534864, 2025). "Significant upregulation of STING, IRF3, TLR7, MAVS, and IFNβ expression was found in COVID-19 exposed placentas vs. controls (p<0.01 for STING, TLR7, MAVS, and IFNβ, and p<0.05 for IRF3)." (PMID 36743911, 2022). "The higher levels of OAS1 and MAVS observed in COVID-19 indicates activation induced by SARS-CoV-2 whilst the absence of differences between IFN-1α levels may be due to downregulation of T cell activation in this group." (PMID 41468475, 2025). "COVID-19 cases displayed higher expression of mRNA levels of MAVS, OAS-1, and SOCS3 (p < 0.05)." (PMID 41468475, 2025). "Whilst mRNA levels of IFN- γ, IFN-1α, MAVS, IL-6, SOCS1 and SOCS3 were similar between LTBi positive individuals in the HC and COVID-19 groups." (PMID 41468475, 2025). "The increased expression of OAS1, MAVS and SOCS3 mRNA in COVID-19 was consistent for both active and recovered cases." (PMID 41468475, 2025). "Individuals in the COVID-19 group showed higher expression of OAS1 (p = 0.0002), MAVS (p = 0.0001) and SOCS3 transcripts (p = 0.001) as compared to HC." (PMID 41468475, 2025). "Pantethine inhibited this increase in MAVS and IRF3 expression in infected cells, as well as that of STING, which controls aberrant type I IFN production and cell death in COVID-19 through c-GAS-STING signaling." (PMID 36754974, 2023). "We observed that TLR7, together with MAVS, TLR9, IRF7, was downregulated in pDCs in the COVID-19 groups but more so in the groups with severe disease." (PMID 36439166, 2022). "Regarding antiviral immune response, we observed elevated mRNA expression of RIG-I, MAVS, and IRF-3 in COVID-19 patients evidencing intracellular recognition of the virus." (PMID 35173744, 2022). "Of these, nine ISGs were differentially regulated in Asymptomatic versus mild COVID-19 cases; IFNAR2, IRF2BP1, IRF4, MAVS, and TRIM14 were upregulated; whilst IRF2BP2, IRF2BPL, and SOCS3 were downregulated." (PMID 34824360, 2021). "The N protein of SARS-CoV-2, the etiological agent of COVID-19, also has been shown to inhibit IFN induced by SeV, poly(I:C), RIG-I, MAVS, TBK1, and IKKε." (PMID 34220846, 2021). "Although these participants were recruited at different times after recovery, we were able to show a consistent result for MTB-stimulated IFN-γ SPUs as well as gene expression levels of OAS1, MAVS and SOCS3 between COVID-19 sub-groups in comparison with controls." (PMID 41468475, 2025). "However, we found higher levels of OAS-1, MAVS and SOCS3 in COVID-19 cases as compared to HC group." (PMID 41468475, 2025). "Furthermore, it is worth noting that SARS-CoV-2 could cause coronavirus disease 2019 (COVID-19), and has a non-negligible correlation with RIG-I, MAVS, and MDA5 as well as their involvement in IFN-Is signaling in this process." (PMID 38124132, 2023).
influenza (17 papers, 2011 to 2024). An acute viral infection of the respiratory tract, occurring in isolated cases, in epidemics, or in pandemics; it is caused by serologically different strains of viruses (influenzaviruses) designated A, B, and C, has a 3-day incubation period, and usually lasts for 3 to 10 days. "In contrast, MTEC deficient in MAVS were unable to produce IFNs in response to influenza infection, suggesting involvement of the RIG-I pathway." (PMID 24278020, 2013). "As we summarized, for example, acetate increases the production of IFN1s with antiviral effects through NLRP3-mediated activation of MAVS located on mitochondria, and, in addition, he restores pathogenic bacterial phagocytosis in macrophages after influenza infection." (PMID 37928517, 2023). "Collectively, our findings define the Mfn2-SYVN1 axis as a new signaling cascade for proteasome-dependent degradation of MAVS and a ‘fine tuning’ of antiviral innate immunity in response to influenza infection under stress." (PMID 32943610, 2020). "In this study, MAVS−/− mice were compared with C57BL/6J mice to evaluate key factors in the RLRs signaling pathway after influenza infection." (PMID 31757053, 2019). "Lung expression of RIG-I and MDA5 was modestly upregulated following influenza infection in MAVS KO mice as compared with WT mice, suggesting that there was attempted compensation for MAVS KO by overexpression of RIG-I and MDA5." (PMID 30532653, 2018). "In the present study, MAVS expression on the mitochondrial outer membrane was found significantly elevated by vitamin C administration on the 4th day after influenza infection." (PMID 25710018, 2015). "The restored MAVS expression also facilitates the antiviral reaction in influenza infected stressed mice." (PMID 25710018, 2015). "Administration of a MAVS peptide fused to a membrane permeable domain from the HIV Tat protein, induced production of Type I IFN and contributed to protection from lethal influenza infection." (PMID 31242236, 2019). "The results suggest that FTA functions as an anti-influenza agent by downregulating RIG-I, MAVS, and NF-κB p65, the key factors of the RLRs signaling pathway." (PMID 31757053, 2019). "We have previously characterized host-response to influenza infection in human primary macrophages using traditional 2-DE based proteomics and shown that actin and RIG-I/MAVS signaling components translocate onto mitochondria upon infection." (PMID 21589892, 2011). "RIG-I has a pivotal role as a sensor of influenza, and other negative-strand RNA viruses, to promote MAVS-2CARDs interactions." (PMID 32188146, 2020). "In contrast, Nlrx1-/- mice have reduced interferon responses during influenza independent of MAVS interactions." (PMID 26367386, 2015). "In agreement, MAVS−/− mice treated with 5′pppRNA did not control influenza lung titers (5-fold increase vs. wt mice) and the titer was comparable to untreated wt mice." (PMID 23633948, 2013). "Thus, influenza infection of airway epithelia induces, via a RIG-I/MAVS/IRF7 dependent pathway, both type I and III IFNs which drive two overlapping and redundant amplification loops to upregulate antiviral genes." (PMID 24278020, 2013). "Thus, FTA can significantly reduce lung inflammation in C57BL/6J mice but not in MAVS−/− mice, indicating the involvement of the RLRs signaling pathway in the anti-influenza role of FTA." (PMID 31757053, 2019).
colorectal cancer (14 papers, 2013 to 2025). A primary or metastatic malignant neoplasm that affects the colon or rectum. "MAVS dependence was recapitulated in other colorectal cancer lines with STING pathway deficiency, whereas in cells with intact STING signaling, the STING pathway was required for IFN induction by AURKi." (PMID 38358346, 2024). "Recently, activation of the MDA5/MAVS RNA recognition pathway was suggested as an underlying mechanism of decitabine-induced cytotoxicity in colorectal cancer-initiating cells, and its role in myeloid neoplasm requires further elucidation." (PMID 27307795, 2016). "In colorectal cancer, circRERE plays the role of a molecular sponge by competitively binding to miR-6837-3p, thereby protecting mitochondrial antiviral signaling protein (MAVS) mRNA from degradation and promoting anti-tumor immunity." (PMID 39090090, 2024). "To determine whether the response to alisertib was MAVS dependent in colorectal cancer cells, we made CRISPR KOs of MAVS or STING in HT-29, CT26, Ls174T, and SW1417 cell lines and assayed for IFN pathway induction in response to AURKis." (PMID 38358346, 2024). "Accordingly, it is rational to deduce the signal propagation from MAVS to GFPT1 as follows: in mitochondria, as an important innate immunity protein, MAVS may response to colorectal cancer in a very early stage." (PMID 23586028, 2013). "In colorectal cancer, GFPT1 is connected to mitochondrial antiviral-signaling protein (MAVS) from early to late stages, supporting reprogrammed metabolic states seen in viral immune responses." (PMID 40830088, 2025). "Azacytidine is reported to induce anti-tumour effects through the activation of RNA sensors RIG-I/MAVS and the TLR3 pathways in ovarian, and colorectal cancers." (PMID 35998812, 2022). "It was suggested through our signal propagation analysis that MAVS responded to colorectal cancer in the early stage and then transmitted the disease signal to GFPT1 whose dysfunction further accelerated the colorectal cancer patients into late stage." (PMID 23586028, 2013). "Similarly, treatment with an aurora kinase inhibitor (AURKi) in colorectal cancer has been shown to activate the type I IFN response, which is dependent on MAVS and RIG-I expression." (PMID 39897033, 2025). "Subsequently, the mitochondrial adaptor protein MAVS (mitochondrial antiviral-signaling protein) is activated and leads to enhanced IFN-I signaling, promoting radiosensitivity in murine embryonic fibroblasts (MEFs), glioblastoma (GBM), and colorectal cancer (CRC)." (PMID 34830176, 2021). "Furthermore, knock-down of MAVS also abolished the observed DAC-mediated reduction in frequency of cancer-initiating cells in colorectal cancer cell lines and in primary colorectal cancer cells." (PMID 28359286, 2017). "Similarly, in colorectal cancer, brief exposure to low doses of 5-AZA-CdR can induce dsRNA expression, activating the cytoplasmic pattern recognition receptor MDA5 and subsequently engaging downstream effectors MAVS and IRF7 to target colorectal cancer cells." (PMID 39329125, 2024).
hepatoma (14 papers, 2008 to 2026). "GP73 expression is activated and correlated with IFN-β production during HCV infection in patients’ serum, primary human hepatocytes (PHHs) and human hepatoma cells through mitochondrial antiviral signaling protein (MAVS), TNF receptor-associated factor 6 (TRAF6) and MEK/ERK pathway." (PMID 28394926, 2017). "Using full-length viral constructs, we tested the human hepatoma cell line (Huh-7.5) containing a MAVS cleavage reporter where upon HCV NS3-4A cleavage of the reporter, the RFP translocates to the nucleus." (PMID 34422054, 2021). "This study first investigated the effects of asunaprevir on hepatoma cells, and found interestingly that asunaprevir activates innate immunity in a MAVS dependent manner in hepatoma cells." (PMID 28473813, 2017). "Initially, HCV infection activates GP73 in patients’ serum, primary human hepatocytes (PHHs) and human hepatoma cells by regulating MAVS/TRAF6 and MEK/ERK pathway." (PMID 28394926, 2017). "Although in this study we could confirm peroxisomal localization of MAVS in the human hepatoma cell line Huh7, it is still unclear how MAVS is targeted to this organelle." (PMID 26588843, 2015). "For instance, the Huh7.5 cells, which were cloned from the hepatoma Huh7 cells for their efficacy to support HCV replication, are unable to stimulate IFN induction because of a T55I substitution in the first CARD domain of RIG-I that prevents the association of RIG-I with MAVS." (PMID 20485506, 2010). "Overexpression of RIG-I in hepatocellular carcinoma (HCC) promoted the polarization of M1 macrophages in vitro and increased cancer cell apoptosis in vivo through RIG-I/MAVS/NF-κB pathway." (PMID 35413927, 2022). "In a human hepatoma cell line, it was demonstrated that the nucleotide-binding domain of NLRX1 attenuates hepatitis C virus (HCV)-triggered RIG-I-MAVS signaling by recruiting poly(rC) binding protein 2 (PCBP2) to MAVS." (PMID 33525671, 2021). "Recent study reported that MDA5 plays a major role in IFN response during HCV infection by introducing a mutant MAVS (MAVS-C508R, resistant to NS3/4A cleavage) into human hepatoma Huh7 cells." (PMID 28394926, 2017). "However, data presented in some studies performed using Huh7 hepatoma cells infected with cell-culture generated JFH1 virus showed that the IFN pathway was poorly activated even before full cleavage of MAVS, since only limited nuclear translocation of IRF3 could be detected." (PMID 20485506, 2010). "A cytosolic dsDNA-signaling pathway, mediated by the RNA helicase RIG-I and MAVS, and leading to the induction of IFN-β has been recently demonstrated in human hepatoma cells." (PMID 19008951, 2008). "Thus, GP73 expression is activated and correlated with IFN activation through MAVS and probably through MAVS-mediated MEK/ERK pathway during HCV infection in human serum, primary human hepatocytes and human hepatoma cells." (PMID 28394926, 2017).